MASP2 (MBL associated serine protease 2)
Diseases named in the same sentence as MASP2 in open-access papers (continued):
Sharing a sentence is not in itself a finding about the gene and the disease.
lung carcinoma (1 paper, 2020). "Moreover, an early postoperative reduction in MBL, CL-L1, H-ficolin, M-ficolin, MASP-3, MAp44, MASP-2, and MAp19, but not MASP-1, was recently reported in lung cancer patients undergoing thoracoscopic lobectomy." (PMID 32267878, 2020).
meningitis (1 paper, 2017). A disorder characterized by acute inflammation of the meninges of the brain and/or spinal cord. "Masp2 deficiency was previously shown to increase the risk of infection but we now show this leads to a reduced inflammatory response during meningitis, thereby improving survival." (PMID 28086930, 2017).
myocardial ischemia (1 paper, 2012). A disorder of cardiac function caused by insufficient blood flow to the muscle tissue of the heart. "The C4-bypass activation of the lectin pathway was shown to play a significant physiological role in ischemia-reperfusion injury; MASP-2 deficient mice are protected from reperfusion injury following myocardial ischemia, whereas C4 deficient mice are not." (PMID 22792067, 2012).
nephritis (1 paper, 2020). Inflammation of renal tissue. "SLE patients with nephritis (N = 30) revealed higher expression of MASP2 than that in patients without nephritis (N = 31) (12 518.77 ± 847.03 vs 11 951.58 ± 598.88 pg/mL, P = .004)." (PMID 32677764, 2020).
papillary thyroid carcinoma (1 paper, 2014). "Moreover, elevated MASP-2 levels in children with tumours of the central nervous system and in patients with papillary thyroid carcinoma have been reported." (PMID 25038892, 2014).
preeclampsia (1 paper, 2024). Preeclampsia is a hypertensive disorder of pregnancy that is characterized by new-onset hypertension with proteinuria presenting after 20 weeks of gestation, and depending on mild or severe forms may initially present with severe headache, visual disturbances, and hyperreflexia. "Furthermore, the investigation identified a number of genetic variants in the genes of ADAMTS13, C3, CFH, CFB, thrombomodulin, MBL2, and MASP2 that were significantly linked with the occurrence of preeclampsia, according to the results of analyses A and B." (PMID 38673014, 2024).
pulmonary TB (1 paper, 2021). "While a recent study reported three instances of MASP2 rs72550870 variant, two in people with pulmonary TB and one completely healthy person." (PMID 33753877, 2021).
sporotrichosis (1 paper, 2021). The commonest and least serious of the deep mycoses, characterized by nodular lesions of the cutaneous and subcutaneous tissues. "Variations in the PRR MBL and mannose-binding lectin-associated serine protease-2 (MASP-2) proteins were shown to be responsible for sporotrichosis in the Chinese population." (PMID 34490039, 2021).
thrombosis (1 paper, 2020). "Here, the predominant lesion in the lung was microvascular thrombosis associated with MASP‐2, C4 and C5b‐9 deposition with colocalisation for SARS‐CoV‐2 S protein, but with relative sparing of alveolar cells." (PMID 32559343, 2020). "The procoagulant effects of MASP‐1 and MASP‐2 (described earlier) coupled with the prothrombotic effects of C5a and MAC on endothelium could then predispose to microvascular thrombosis." (PMID 32559343, 2020).
vasculitis (1 paper, 2016). "In addition, glomerular deposition of C3 in MASP‐2‐deficient mice with anti‐MPO vasculitis was similar to that in wild‐type mice." (PMID 27235854, 2016).
veno-occlusive disease (1 paper, 2024). "Inhibition of MASP-2 may provide therapeutic benefits for TA-TMA and potentially other endothelial injury syndromes, including veno-occlusive disease/sinusoidal obstruction syndrome (VOD/SOS)and GVHD." (PMID 38763940, 2024).
ZIKV infection (1 paper, 2023). "The lack of induction of MASP1 and MASP2 suggests that the lectin pathway is not induced and that this increase in C2 and C4a reflects an increase in the classical pathway by ZIKV infection." (PMID 37022660, 2023).
infection (16 papers, 2009 to 2026). The state of being infected such as from the introduction of a foreign agent such as serum, vaccine, antigenic substance or organism. "Early elevations of MASP2 make it an attractive diagnostic biomarker candidate as its presence corresponds to infection and can differentiate active infection from the sterile post-operative inflammation associated with catheter insertion." (PMID 38881889, 2024). "Biallelic pathogenic variants in this gene are an established cause for autosomal recessive MASP2 deficiency, manifesting with increased susceptibility to infection due to the defective activation of the complement system." (PMID 39062917, 2024). "MASP-2 antibody treatment was associated with lower plasma levels of TNF-α compared to saline at 48 h after infection (median 0.10 vs. 0.25 ng/ml, P = 0.044)." (PMID 28086930, 2017). "75% of the WT mice survived the infection, compared with only 20% of the MASP-2 deficient mice (p = 0.0006)." (PMID 22792067, 2012). "This variant has been described for the first time in a patient with an inherited deficiency of MASP2, who was characterized by augmented susceptibility to infection and development of immunological disease." (PMID 19405982, 2009). "To examine the hypothesis that polymorphisms of the MASP2 gene in SARS patients are genetic factors that influence infection susceptibility, we studied MASP2 gene polymorphisms in DNA from two groups of Chinese SARS patients, and compared these with normal blood donors from the same region." (PMID 19405982, 2009). "Using our murine model of S. epidermidis catheter infection we quantified levels of the complement components C1q, Factor B, MASP2, C3, and C5 over the course of infection along with bacterial burdens." (PMID 38881889, 2024). "Results show that several rare pathogenic/likely pathogenic genomic variants in genes CFTR, MASP2, MEFV, TNFRSF13B, and RNASEL likely contribute to the severe infection outcomes in our patient cohort." (PMID 39062917, 2024). "MASP2 was significantly increased at day one post-infection, suggesting that the lectin pathway predominates at this time point." (PMID 38881889, 2024). "The level of MASP-2 in plasma plays a dual role in the infection and progression of infectious diseases." (PMID 33753877, 2021). "At 20 h post-infection, all mice were treated with ceftriaxone intraperitoneally plus either MASP-2 antibodies (n = 18) or saline (n = 18) and euthanized at 24 and 48 h." (PMID 28086930, 2017). "Plasma C5b-9 levels were reduced in MASP-2 antibody-treated mice compared to saline-treated mice at 24 h after infection (0.42 vs. 0.63 μg/ml, P = 0.022)." (PMID 28086930, 2017). "Brain albumin content was elevated in Masp2−/− (312.23 vs. 86.27 μg/mg tissue, P = 0.006) and WT (262.21 vs. 42.85 μg/mg tissue, P < 0.001) mice at 30 h after infection compared to saline-inoculated mice." (PMID 28086930, 2017). "Bacterial outgrowth in CSF, blood, brain, spleen, and lung was similar between Masp2−/− and WT mice at 6 and 30 h after infection." (PMID 28086930, 2017). "Next, we infected Masp2−/− (n = 24) and WT (n = 24) mice by intracisternal inoculation with S. pneumoniae and euthanized them at 6 and 30 h after infection." (PMID 28086930, 2017). "Complement activation, as indicated by brain levels of C5b-9, was also similar between Masp2−/− and WT mice 30 h post-infection (P = 0.88)." (PMID 28086930, 2017). "If this mechanism is operating in mycobacterial cell invasion, low MASP-2 levels would be insufficient to avoid subsequent infection." (PMID 23935922, 2013). "During the first 12 hours after infection, the WT mice showed signs of an initial clinical response (hunching), while the MASP-2−/− mice appeared unaffected." (PMID 22792067, 2012). "Therefore, EGCG in tea leaves and MASP-2 can both interact with macrophages directly or indirectly to affect the host infection with MTB." (PMID 33753877, 2021).
infection (continued). "MASP-2 antibody-treated mice had reduced brain levels of C5b-9 compared to saline-treated mice at 24 h (median 1.08 vs. 2.53 μg/mg tissue, P = 0.017) and 48 h (0.85 vs. 1.25 μg/mg tissue, P = 0.052) after infection." (PMID 28086930, 2017). "MASP-1 and MASP-2 can be activated during infection or stressful conditions." (PMID 21625439, 2011). "The remaining 67 mice all showed signs of infection 20 h post-infection and were randomized for antibiotic therapy consisting of ceftriaxone intraperitoneally in combination with either saline (n = 22), isotype antibodies (n = 23), or MASP-2 antibodies (n = 22)." (PMID 28086930, 2017). "The lectin pathway of the complement system activates after infection and oxidative stress on endothelial cells generating active serine proteases: MASP-1 and MASP-2." (PMID 21625439, 2011). "Masp2−/− mice had significantly lower brain levels of interleukin (IL)-1β (median 3.46 vs. 5.33 ng/mg tissue, P = 0.045), IL-10 (1.04 vs. 1.70 ng/mg tissue, P = 0.038), and TNF-α (9.32 vs. 22.58 ng/mg tissue, P = 0.025) compared to WT mice at 30 h after infection." (PMID 28086930, 2017). "Similarly, under either normal or infection-inflammation condition, CRP and MASP-2 did not compete with each other for L-ficolin." (PMID 19180241, 2009).
cancer (13 papers, 2014 to 2025). A tumor composed of atypical neoplastic, often pleomorphic cells that invade other tissues. "Furthermore, increased levels of LP proteins are reported in cancer patients and increased pre- and postoperative MASP-2 levels have been associated with poor prognosis after cancer surgery." (PMID 32267878, 2020). "High MASP-2 levels concentration in serum significantly correlated with recurrent cancer disease and with poor survival, thus the MASP-2 level had an independent prognostic value in the patients." (PMID 32998690, 2020). "Reduced perioperative levels of MBL, M-ficolin, MASP-1, MASP-3, MAp44, and MASP-2 have previously been found in cancer patients undergoing laparoscopic colectomy." (PMID 32267878, 2020). "MASP-1, MASP-2, MASP-3, MAp-44, and MAp-19 serum concentrations in patients with cervical lesions and cancer." (PMID 30532757, 2018). "When patients who died and those who experienced relapse of CIN or cancer during follow-up were considered, only MASP-2 and MAp-19 were significantly different." (PMID 30532757, 2018). "Cancers studied here seem in general to affect concentrations of complement activating collectins and MASP-2 disparately in males and females." (PMID 30294330, 2018). "However, other previous studies reported increased concentrations of MBL and MASP-2 and increased MBL/MASP activity in cancer patients." (PMID 32267878, 2020). "Given the lack of research on MASP2 in NPC, further studies are needed to explore its potential as a biomarker for cancer and NPC, specifically." (PMID 40565234, 2025).
tumor (8 papers, 2014 to 2025). "MASP-2 detected by immunohistochemistry employing a specific monoclonal antibody revealed its presence in both cytoplasm and nuclei of tumour cells." (PMID 35326694, 2022). "A high concentration of MASP-2 easily promotes inflammation and proliferation, leading to tumor invasion and metastasis." (PMID 32903484, 2020). "Furthermore, in contrast to ficolin genes, the ovarian expression of MBL2 and MASP2 was significantly higher in ovarian sections from malignant tumours compared with benign tumours or normal tissue." (PMID 35326694, 2022). "It is possible that patients with higher serum levels of MASP-1 and/or MASP-2 present exacerbate activation of complement leading to the disturbance of the basement membrane, and ultimately to its damage or rupture and consequently, tumor invasion." (PMID 30532757, 2018). "However, the highest frequency of the A/G (MASP2) and LXA/O or O/O (MBL2) genotypes was found among OC patients with tumours of G1–2 grade (well/moderately differentiated).Furthermore, MBL deficiency-associated genotypes predicted prolonged survival." (PMID 25038892, 2014). "High levels of MASP-2 and MASP-1 may increase activation of the complement system by the lectin pathway, thereby augmenting the release of C5a, a potent anaphylatoxin that activates cellular responses involved in tumor growth and progression." (PMID 30532757, 2018).
bacterial infections (3 papers, 2020 to 2023). "The downregulated proteins were related to the reduction in markers of inflammation (e.g., Alox5, Lbp, C5, Il36b, and Mmp8) and bacterial infections (e.g., Masp2, Mbl1, Krt34, and Cfd)." (PMID 38030636, 2023).
infectious disease (3 papers, 2017 to 2020). A disorder directly resulting from the presence and activity of a microbial, viral, or parasitic agent in humans. "The identified role of MASP-2 is consistent with the two-edged sword theory on complement activation in infectious disease." (PMID 28086930, 2017).
renal disease (3 papers, 2019 to 2025). "This indicates that therapeutic targeting of MASP-2 in proteinuric nephropathies may offer a useful strategy in the clinical management of proteinuria associated pathologies in a variety of different underlying renal diseases." (PMID 31608060, 2019). "Twenty-one kidney biopsies of different proteinuric kidney diseases were stained for complement components MASP-2 (lectin pathway), C1q (classical pathway), properdin (alternative pathway) and downstream complement activation (C3d and C5b-9), as well as syndecan-1." (PMID 41215783, 2025).
benign tumours (2 papers, 2014 to 2022). "The MASP2 gene relative expression was significantly higher in malignant ovaries compared with normal organs or those affected by benign tumours." (PMID 25038892, 2014).
autosomal dominant disease (1 paper, 2024). Autosomal dominant form of disease. "Although MBL deficiency is considered an autosomal dominant disease, similar to MASP2 deficiency, it is a common deficiency, and patients may remain asymptomatic." (PMID 39062917, 2024).
colorectal (1 paper, 2023). "High MASP-2 concentration is associated with poor prognosis in patients with colorectal cancer." (PMID 36991043, 2023).
MASP2 also shares sentences with these, for which no sentence is quoted: lupus nephritis (3 papers); Sjogren syndrome (3); ankylosing spondylitis (2); arterial hypertension (2); atypical hemolytic-uremic syndrome (2); autoimmune disease (2); C3 glomerulopathy (2); injury (2); lepromatous leprosy (2); lung adenocarcinoma (2); non-Hodgkin lymphoma (2); osteoarthritis (2); rheumatic diseases (2); thymoma (2); acute kidney failure (1); anemia (1); benign ovarian tumours (1); brain inflammation (1); brain injury (1); calcium oxalate kidney stone (1); cardiovascular disease (1); Cataplexy (1); cerebrovascular disease (1); Chagas cardiomyopathy (1); chronic obstructive pulmonary disease (1); cold agglutinin disease (1); colitis (1); Dengue virus infection (1); dermatosparaxis (1); endometritis (1).
A further 25 diseases each share a sentence with MASP2 in 1 paper.